IL1A (interleukin 1 alpha)
Diseases named in the same sentence as IL1A in open-access papers (continued):
Sharing a sentence is not in itself a finding about the gene and the disease.
brucellosis (2 papers, 2021 to 2025). Brucellosis is a bacterial infection that spreads from animals to people via unpasteurized dairy products or by exposure to contaminated animal products or infected animals. "Similarly, we observed that Mediterranean Buffaloes with brucellosis release lower levels of three pro-inflammatory cytokines than healthy controls: IL-1α, IL-1β, IL-6." (PMID 40406273, 2025). "Microarray analysis of lung tissue homogenates and BALF cells revealed that RTD-1 significantly reduced proinflammatory gene expression, particularly inflammasome-related genes (nod-like receptor protein 3, Mediterranean fever gene, interleukin (IL)-1α, and IL-1β) relative to the control." (PMID 34572625, 2021). "From the initial 15, we narrowed it down to five: our analysis showed that the quantitative determination of IFN-γ, in parallel with the chemokine IP-10 and three pro-inflammatory cytokines (IL-6, IL-1α and IL-1β) could be useful in the diagnosis of brucellosis in Mediterranean Buffaloes." (PMID 40406273, 2025).
cardiac arrest (2 papers, 2015 to 2021). Cessation of breathing and/or cardiac function. "In muscle, similar differences between “cardiac arrest group” animals and “injury group” were also seen, along with marked increases in IL-18, IL-1α, IL-6, IFNγ, and MCP-1." (PMID 26635801, 2015). "In skin, the levels of IL-18 and IL-1α present in “cardiac arrest group” animals were much higher than those seen in any other groups." (PMID 26635801, 2015). "The blood levels of IL-1α and IL-1β also similarly increased after cardiac arrest in both groups." (PMID 34774087, 2021). "Notably, IL-1α and IL-18, along with caspase-1, were greatly elevated in the skin following cardiac arrest, consistent with differential inflammasome activation." (PMID 26635801, 2015). "Cardiac arrest greatly elevates IL-1α, IL-18, and caspase-1 in the skin." (PMID 26635801, 2015).
cerebral edema (2 papers, 2021 to 2023). "Studies have shown that dexamethasone, commonly used for the management of cerebral edema, inhibits TAM production of IL-1β, and genetic ablation of IL-1α/β or IL-1β in a murine GB model or the administration of a potential IL-1β inhibitor (Sulfasazaline) reduces cerebral edema." (PMID 37355636, 2023).
chondrosarcoma (2 papers, 2005 to 2014). A malignant cartilaginous matrix-producing mesenchymal neoplasm arising from the bone and soft tissue. "Also IL-1β and IL-1α were induced by IL-1β treatment, showing a feed-forward effect and demonstrating that stimulated chondrosarcoma cells are able to produce these cytokines." (PMID 24901233, 2014).
chronic heart failure (2 papers, 2011 to 2025). "Proinflammatory cytokines such as IL-1α, IL-1β, TNF-α, and TNFR2 are elevated in animal models and patients with chronic heart failure." (PMID 40072051, 2025).
chronic hepatitis C (2 papers, 2022 to 2023). "It is also documented that liver-infiltrating T cells from chronic hepatitis C patients produced IFN(interferon)-γ, apoptotic hepatocytes released IL-1α, and macrophages exposed to HCV secreted IL-1β and IL-18." (PMID 36901973, 2023). "It is also documented that liver-infiltrating T cells from chronic hepatitis C patients produce IFN-γ, apoptotic hepatocytes release IL-1α, and macrophages exposed to HCV induce IL-1β and IL-18 secretion." (PMID 35887291, 2022).
colon adenocarcinoma (2 papers, 2021 to 2023). "Survival analysis on GEPIA using colon adenocarcinoma data set screened 5 genes CXCL3, IL1B, IL1A, MET and TNS1 that have significant log rank p value in Kaplan–Meier survival analysis." (PMID 34083590, 2021).
corneal disease (2 papers, 2024 to 2025). "To determine if IL-1β regulates corneal disease severity caused by MRSA, we injected 1×103 log phase the common MRSA isolate USA300 directly into the corneal stroma of IL-1α−/−, IL-1β−/−, and IL-1α/β−/− mice." (PMID 41415470, 2025).
cryptococcal infection (2 papers, 2017 to 2022). "Induction of IL-1α/β during mouse cryptococcal infection has been reported, but a clear role for IL-1R-dependent signaling in the host immune response has not been demonstrated." (PMID 29403476, 2017). "Interleukin-1 alpha (IL-1α) and interleukin-1 beta (IL-1β) are pro-inflammatory cytokines that are induced after Cryptococcus neoformans infection and activate the interleukin-1 receptor type I (IL-1RI)." (PMID 29403476, 2017). "Our observation that both IL-1α and IL-1β were induced in the lungs of BALB/c mice after intratracheal infection with C. neoformans 52D is also consistent with earlier reports that associated the induction of IL-1β in lung and brain with resistance to cryptococcal infection." (PMID 29403476, 2017).
developmental delay (2 papers, 2021 to 2022). "Using a larger sample set, a subsequent analysis found high levels of many cytokines, including IL-1α and IL-6, in mothers of children with ASD and developmental delay compared with children with ASD without developmental delay and controls." (PMID 35222122, 2022).
eczema (2 papers, 2013 to 2017). "There was an increase in the expression of a number of cytokines and soluble immune mediators, including IL-1a, a protein with levels known to be increased in barrier-defective skin and skin of subjects with eczema, which was subsequently confirmed by means of immunofluorescence." (PMID 27913303, 2017).
emphysema (2 papers, 2019 to 2021). "Remodeling of the ECM by various MMPs is modulated by pro-inflammatory cytokines such as TNFα, IL-1α, and TGFβ, which are implicated in the pathogenesis of emphysema." (PMID 31234847, 2019). "The overexpression of IL-1α in lung epithelium of mice exposed to smoke was involved in the development of COPD-like phenotype consisting of emphysema, lung inflammation and fibrosis." (PMID 34084280, 2021).
endometrial tumor (2 papers, 2021 to 2025). "The concentration of IP-10, PDGF-AA, TGFα, fractalkine, IL-1α, IL-15, IL-13, sCD40L, VEGF, PDGF-BB, IL-17, RANTES, IL-1Ra and IL-8 trended higher in CM from endometrial tumors than that measured in CM from adjacent non-cancerous tissue." (PMID 33968059, 2021).
eosinophilia (2 papers, 2020 to 2025). "In the asthmatic EMTU, the epithelial release of inflammatory cytokines (CCL-5, IL-1α, TNF-α, IL-8, and IL-6) can regulate mesenchymal inflammation to cause eosinophilia and TH2 inflammation (TSLP, GM-CSF) as well as neutrophilic inflammation (TNF-α, IL-8, IL-6)." (PMID 32679790, 2020).
esophageal squamous cell carcinoma (2 papers, 2021 to 2023). Esophageal squamous cell carcinoma (ESCC) is a type of esophageal carcinoma (EC) that can affect any part of the esophagus, but is usually located in the upper or middle third. "In esophageal squamous cell carcinoma (ESCC), differentially methylated CpG sites between cancer tissue and healthy tissue were found in genes in the IL10 signaling pathway; IL-6 was found to be hypomethylated, while IL-1α was found to be hypermethylated." (PMID 34901003, 2021).
experimental autoimmune encephalomyelitis (2 papers, 2019 to 2022). An autoimmune demyelinating disease of the central nervous system that is produced experimentally in animals by the injection of homogenized brain or spinal cord in Freund's adjuvant. "Increased IL‐1α expression has previously been identified in a subset of disease‐associated microglia in an experimental autoimmune encephalomyelitis model, though whether it is important in the pathology is unknown." (PMID 35137954, 2022). "Furthermore, mice deficient in both IL-1α and IL-1β do not develop experimental autoimmune encephalomyelitis (EAE), which is caused by pathogenic TH17 cells." (PMID 31840109, 2019).
familial cold autoinflammatory syndrome (2 papers, 2023 to 2024). Familial cold urticaria (FCAS) is the mildest form of cryopyrin-associated periodic syndrome (CAPS) and is characterized by recurrent episodes of urticaria-like skin rash triggered by exposure to cold associated with low-grade fever, general malaise, eye redness and arthralgia/myalgia. "Rilonacept is an IL-1 receptor fusion protein consisting of the Fc portion of human IgG1 and the human IL-1 receptor which traps both IL-1α and IL-1β, and clinically used for familial cold autoinflammatory syndrome (FCAS), Muckle–Wells syndrome (MWS), and recurrent pericarditis." (PMID 37881433, 2023).
familial hypercholesterolemia (2 papers, 2023 to 2024). An inheritable form of hyperlipidemia, in which there are excess lipids in the blood. "The translocation of IL-1α to the cell surface was regulated by myristoylation and increased in mice with hypercholesterolemia." (PMID 37701434, 2023).
female infertility (2 papers, 2020 to 2025). Diminished or absent ability of a female to achieve conception. "489TT/HHV-6A positive women also showed higher levels of IL-1β, IL-1α, and IL-8 (CXCL8) suggesting that the 489TT gain-of-function variant not only favors virus entry but also triggers a wide inflammatory response that might contribute to female infertility." (PMID 32153407, 2020). "Of the potential CIPs, IL2 and IL1A had the highest combined score (0.997) in male infertility, and OSM and LIFR had the highest combined score (0.999) in female infertility." (PMID 40070583, 2025).
Fulminant hepatic failure (2 papers, 2017 to 2019). Hepatic failure refers to the inability of the liver to perform its normal synthetic and metabolic functions, which can result in coagulopathy and alteration in the mental status of a previously healthy individual. "In conclusion, this study illustrated the contribution of both IL-1α and Il-1β in the development and acceleration of fulminant hepatitis failure." (PMID 28953903, 2017).
Heat Stroke (2 papers, 1993 to 2023). A condition caused by the failure of body to dissipate heat in an excessively hot environment or during PHYSICAL EXERTION in a hot environment. "The authors reported recently that endotoxaemia mediated elevated levels of tumour necrosis factor (TNF-α) and interleukin-1α (IL-1α) were involved in the pathophysiology of acute heat stroke patients." (PMID 18475549, 1993).
Hypercalcemia (2 papers, 2017 to 2019). An abnormally increased calcium concentration in the blood. "Because many activators of IL-1α secretion, described by Tschopp group, are inducers of Ca2+ influx and patients with disseminated PCM present hypercalcemia, we suppose that calpain-like proteases can also influence IL-1α cleavage after P. brasiliensis stimulation." (PMID 31425553, 2019). "In addition, EC-GI ( a cell line derived from a human patient with esophageal carcinoma and hypercalcemia) cancer xenograftsin nude mice resulted in HHM that was mediated by the synergistic actions of PTHrP and IL-1α." (PMID 29056680, 2017).
Hyperkeratosis (2 papers, 2014 to 2016). Hyperkeratosis is a histopathological term defining a thickened stratum corneum and may be present in many different skin conditions, with many possible overlaps. "IL-1α is increased in ARCI and has been postulated to be a key cytokine involved in the hyperkeratosis in TGM1 deficiency using a rat organotypic culture model and rat Tgm1 siRNA." (PMID 27442430, 2016). "Finally IL-1α has been described to control expression of numerous genes within the epidermal differentiation complex and IL-1α transgenic mice developed a spontaneous skin disease characterized by scaling, hyperkeratosis and parakeratosis, signs of an altered keratinocyte differentiation." (PMID 25010647, 2014).
hyperthyroidism (2 papers, 2020 to 2021). Overactivity of the thyroid gland resulting in overproduction of thyroid hormone and increased metabolic rate. "However, Asians show different genetic polymorphisms for hyperthyroidism risk: IL-1α at 889 C/T, IL-1β at 511 C/T, IL-6 at 174 G/C, IL-6 at 572 G/C, and IL-10 at 1,082 A/G polymorphisms." (PMID 34567510, 2021). "In concordance, in our study we found higher levels of secreted IL-1α in AITD blood compared with levels in healthy individuals, and its variance was greater in euthyroidism/TPOAb-positive blood and in hyperthyroidism." (PMID 32182948, 2020). "Hence, individuals from 4 categories have the same levels of IL-1α, but there are more inter-individual variabilities in euthyroidism/TPOAb-positive and hyperthyroidism than euthyroidism/TPOAb-negative and hypothyroidism." (PMID 32182948, 2020).
Keratocystic odontogenic tumor (2 papers, 2018 to 2023). An intraosseous odontogenic neoplasm that usually arises from the mandible. "In this study, patients who expressed more IL-1α had a better response to marsupialization, perhaps because UA with high IL-1α expression shares the same biological behavior as odontogenic keratocysts (OKCs)." (PMID 29419674, 2018).
kidney (2 papers, 2020 to 2023). "Although IL-1α showed strong cytoplasmic expression, especially in dilated atrophic renal proximal tubule cells of DN patients, no IL-1β could be detected in any of the kidney DN samples." (PMID 32733443, 2020).
leptospirosis (2 papers, 2016). A contagious bacterial infection caused by spirochetes of the genus Leptospira. "Consistent with our current findings, others and we have shown previously that high levels of proinflammatory cytokines, and their transcripts, IL-1α, IL-6, and IL-8 as well as the IL-1 antagonist receptor 1, are associated with poor disease outcomes for leptospirosis." (PMID 27812211, 2016). "For this, we evaluated the mRNA expression of a panel of immune related cytokines (IL-1α, IL-1β, IL-8, IL-10, TNF-α, TGF-β) and enzymes (5-LO, iNOS) in blood leukocytes from dogs with AKI and leptospirosis, including dogs with and without LAPH." (PMID 26824356, 2016).
lichen sclerosus (2 papers, 2016 to 2022). "Other studies evidenced an inflammatory response in genital LS; the expression of several pro-inflammatory cytokines, such as IFN-γ, TNF-α, IL-1α and IFN-γ receptor, was increased in specimens of vulval lichen sclerosus from adult women compared with specimens of normal vulva and normal skin." (PMID 27649154, 2016). "However, there is almost no data reflecting the expression of cytokines genes in the LS tissue what prompted us to determine the mRNA levels of IL-1A, IL-6, IL-1B, IL-1RN, TGF-β1 and INF-γ genes in a large sample of penile lichen sclerosus tissue as compared to control penile tissues." (PMID 35103930, 2022).
lymphedema (2 papers, 2021 to 2023). Excess fluid collection in tissues, causing swelling. "Pre-surgery level of IL1-a, IL-6, IL-8, and VEGF was associated with the severe symptom class at 8 weeks post-surgery, suggesting that such biomarkers may be used to predict risk for lymphedema symptoms." (PMID 34322193, 2021). "Future studies are warranted to replicate our observation that differences in IL1-α, IL-6, IL-8, and VEGF levels and lymphedema symptoms and to evaluate levels of these biomarkers in relation to lymphedema symptom classes and arm lymphedema in an independent sample." (PMID 34322193, 2021).
male infertility (2 papers, 2018 to 2025). The inability of the male to effect fertilization of an ovum after a specified period of unprotected intercourse. "This is the preliminary report on the association of IL-1α C376A polymorphism with male infertility in theKashan population." (PMID 29935069, 2018). "In this study,we investigated the association of the C376A polymorphism in IL-1α with male infertility in men referring to theKashan IVF Center." (PMID 29935069, 2018). "Additionally, cytokines, such as IL2 and IL1A had the highest combined score in the PPI network associated with male infertility." (PMID 40070583, 2025). "This association shows that the IL-1α gene may be a biomarker for male infertility, and thereforeneeds additional investigations in future studies to validate this." (PMID 29935069, 2018). "Our study suggests that the IL-1α C376A SNP may increasethe risk of male infertility up to two-fold." (PMID 29935069, 2018).
melancholia (2 papers, 2018 to 2022). A subtype of depression characterized by the inability to find pleasure in positive things combined with physical agitation, insomnia, or decreased appetite. "Melancholia was associated with inflammatory mediators (sTNFR80, IL-1α) in the two selected studied (39a)." (PMID 35740389, 2022). "IL-1α (inversely) and sIL-6R (positively) were significantly associated with melancholia." (PMID 29103192, 2018). "Melancholic depression is associated with increased sIL-6R but lowered IL-1α levels." (PMID 29103192, 2018). "We are not aware of any other data linking lowered IL-1α serum levels to melancholia, although increased mitogen-stimulated levels of IL-1β were found in melancholic depression." (PMID 29103192, 2018).
melanosis (2 papers, 2019 to 2024). "Our findings on the autocrine cytokine stimulation associated with UVB melanosis demonstrated that the upregulation of IL-1α is mainly responsible for stimulating the production of EDN1 and SCF in UVB-exposed human keratinocytes." (PMID 31357457, 2019). "Similarly, ET-1 in SL, HGF in DF /SL, KGF in SL /melasma, IL-1α in SL, sFRP-2 in SL /melasma, and NGF in melasma stimulate melanogenesis of human melanocytes." (PMID 38674144, 2024).
meningioma (2 papers, 2025). A generally slow growing tumor attached to the dura mater. "Other cytokines expressed in meningioma such as IL‐1β, IL‐1α, and TNF‐α have not had corresponding receptors detected yet." (PMID 40729436, 2025).
metastatic cancer (2 papers, 2011 to 2020). A carcinoma which has spread from the original site of growth to another anatomic site. "Together, these results indicate that JNK-driven production of IL-1α/β by metastatic cancer cells induces CXCL9/10 in pulmonary MAFs to form a supportive metastatic niche." (PMID 32198421, 2020). "Increased IL-1α expression correlated with the expression of prometastatic (IL-6 and IL-8) and anti-apoptotic genes (TRAF-1 and cIAP-2) and is associated with invasive and metastatic cancer leading to poor prognosis." (PMID 21139583, 2011).
metastatic melanoma (2 papers, 2018 to 2024). A melanoma that has spread from its primary site to another anatomic site. "In metastatic melanoma the BRAFV600E mutation was reported to elevate production of IL-1α and IL-1β, abrogated after treatment with VEM." (PMID 29983861, 2018).
Myocardial fibrosis (2 papers, 2023 to 2024). "These delayed processes are intimately linked to TGF-β signaling, a crucial regulator of cardiac fibroblast activation, myocardial fibrosis and scar formation following MI8, and the possible influence of IL-1α on such processes has not been determined." (PMID 36899010, 2023).
nasopharyngeal carcinoma (2 papers, 2023 to 2024). A carcinoma arising from the nasopharyngeal epithelium. "Nasopharyngeal carcinoma (NPC) is a neoplasm related to inflammation; the expression of cytokines, such as CCL3, CCL4, CCL20, IL-1α, IL-1β, IL-6, IL-8, and IL-10, among others, is presumed to be associated with NPC occurrence and development." (PMID 39483474, 2024). "Nasopharyngeal carcinoma cells treated with PDT showed that IL-8, IL-1α, IL-1β, LC3BI, LC3BII, MMP2, and MMP9 levels were significantly higher than in groups that did not receive PDT." (PMID 37239013, 2023). "Nasopharyngeal carcinoma cells infected with EBV and treated with PDT significantly increased IL-8, IL-1α, and IL-1β levels, resulting in cell death." (PMID 37239013, 2023). "PDT also increased IL-1α and IL-1β levels in nasopharyngeal carcinoma cells without EBV infection, but at a lower rate than tumors infected with EBV." (PMID 37239013, 2023).
Neonatal sepsis (2 papers, 2020 to 2023). Systemic inflammatory response to infection in newborn babies. "Although IL-1β has been implicated during neonatal sepsis, less is known about IL-1α in human neonates." (PMID 32479514, 2020). "The study identified that IL-1α, and not IL-1β, was responsible for IL-1R1-dependent lethality during neonatal sepsis." (PMID 32479514, 2020).